CXCL14 (C-X-C motif chemokine ligand 14)
Diseases named in the same sentence as CXCL14 in open-access papers (continued):
Sharing a sentence is not in itself a finding about the gene and the disease.
colorectal cancer (continued). "However, few studies have reported the potential of CXCL14 in colorectal carcinoma initiation and progression." (PMID 23294544, 2013). "That is why the aim of our study was an effort to elucidate and evaluate the utility of selected CXC-chemokines determination (CXCL5, CXCL14 and CXCL16) in patients with colorectal cancer compared to healthy control." (PMID 37848726, 2023). "Further experiments showed that CXCL14 inhibited the migration, infiltration and epithelial-to-mesenchymal transition (EMT) of colorectal cancer through suppressing the NF-κB signaling pathway." (PMID 35770088, 2022). "For example, in colorectal cancer tissue, CXCL1, CXCL2, CXCL3, CXCL5, CXCL8, and CXCL11 were highly expressed, while CXCL12, CXCL13, and CXCL14 were little expressed." (PMID 36612163, 2022). "The level of CXCL14 expression in primary colorectal carcinoma specimens from 135 late-stage (III/IV) colorectal carcinoma patients stratified these tumors as 67 high- and 68 low-CXCL14-expressing tumors." (PMID 23294544, 2013). "In contrast, knockdown of CXCL14 expression could mitigate the proliferative, migratory and invasive potential of HCT116 colorectal carcinoma cells." (PMID 23294544, 2013). "To evaluate whether CAFs expressing Tr-CAF markers could inhibit tumor progression, we investigated the correlation between the CAF-specific immunohistochemical (IHC) staining levels for these 4 CAF markers; CXCL14, ADAMDEC1, EDNRB, and PROCR, and the clinical outcomes of colorectal cancer patients." (PMID 40759242, 2025). "Further, high CXCL14 immunoreactivity was also found in colorectal cancer tissues, compared to adjacent non-cancerous tissues, by using another antibody recognizing CXCL14, which may rule out the possibility of non-specific staining." (PMID 23294544, 2013). "Therefore, patients with colorectal carcinoma showing elevated CXCL14 expression should be carefully followed-up, while those with no or low CXCL14 expression should avoid being overtreated." (PMID 23294544, 2013).
lung carcinoma (21 papers, 2016 to 2025). "This cutoff point provides 87.4% sensitivity and 85.0% specificity, which indicates that plasma CXCL14 can be used as a potential diagnostic marker for lung cancer." (PMID 35769715, 2022). "Our study demonstrates that CXCL14 might serve as a potential diagnostic and prognostic biomarker in patients with lung cancer." (PMID 35769715, 2022). "Increased levels of CXCL14 mRNA have been detected in LUAD biopsies with a micropapillary pattern, and smoking-induced CXCL14 expression in the human airway epithelium has been implicated in chronic obstructive pulmonary disease (COPD)-mediated lung cancer development." (PMID 36551790, 2022). "In addition, CXCL14 is associated with metastasis of lung cancer." (PMID 37056937, 2023). "Therefore, we preliminarily suggested that CXCL14 could be used as a candidate diagnostic marker for lung cancer." (PMID 35769715, 2022). "CXCL14 might serve as a potential diagnostic and prognostic biomarker in patients with lung cancer." (PMID 35769715, 2022). "The elimination of ACKR2 abolished the CXCL14-promoted phosphorylation of PLCβ3, PKCα, and c-Src and lung cancer cells." (PMID 37056937, 2023). "The present results revealed that ACKR2 plays a critical role in the progression of CXCL14-induced lung cancer." (PMID 37056937, 2023). "Pretreatment with U73122 and GF109203X suppressed c-Src phosphorylation activated by CXCL14 confirmed c-Src-dependent PLCβ3 and PKCα activation mediates CXCL14-induced cell migration in lung cancer cells." (PMID 37056937, 2023). "To verify direct CXCL14 activation of NF-κB mediating EMT and migration, we pretreated lung cancer cells with the inhibitors of IκB kinase α (IKKα) and NF-κB inhibitor α (IκBα) or p65 siRNA to evaluate CXCL14-promoted cell migration and EMT." (PMID 37056937, 2023). "Meta-analysis showed that CXCL14 was upregulated in lung cancer tissues containing adenocarcinoma (LUAD)." (PMID 37056937, 2023). "Our data indicated that endogenous CXCL14 increased EMT-dependent cancer metastasis of lung cancer in mice." (PMID 37056937, 2023). "As a specific receptor for CXCL14 in lung cancer, ACKR2 mediates CXCL14-induced signaling that leads to cell motility." (PMID 37056937, 2023). "Smoking induced expression of CXCL14, which links chronic obstructive pulmonary disease to lung cancer." (PMID 36721112, 2023). "Our findings offer new insights into CXCL14 as a potential therapeutic target for cancer invasion and metastasis of lung cancer." (PMID 37056937, 2023). "Collectively, the expression level of CXCL14 was overexpressed in lung cancer and patients with metastases." (PMID 37056937, 2023). "We first examined the expression profile of CXCL14 in lung cancer tissues by using online lung cancer‐specific database‐the Lung Cancer Explorer (LCE)." (PMID 37056937, 2023). "The most important aspect of the data was that ACKR2 is an essential receptor for CXCL14-promoted lung cancer metastasis." (PMID 37056937, 2023). "To further investigate the role of CXCL14 in lung cancer metastasis, we generated cells with stable overexpressed CXCL14 (CXCL14-OV) and cells with knocked down CXCL14 (CXCL14-KD)." (PMID 37056937, 2023). "In this study, stimulation of lung cancer cells with CXCL14 promoted IKKα, IκBα, and p65 phosphorylation, which was antagonized by the c-Src inhibitor." (PMID 37056937, 2023). "The AUC for the plasma CXCL14 concentration to distinguish patients with lung cancer from patients with BPN was 0.5527 (95% CI, 0.477 to 0.6283), with 47.20% sensitivity and 78.95% specificity at the cut-off value of 2253.0 pg/ml." (PMID 35769715, 2022). "We assessed correlations between the CXCL14 level in urine and the clinicopathological features of lung cancer patients." (PMID 35769715, 2022). "The median CXCL14 concentration in the urine of lung cancer patients was 561.13 pg/ml and that in healthy volunteers was 326.16 pg/ml." (PMID 35769715, 2022).
lung carcinoma (continued). "But the plasma CXCL14 concentration was slightly higher in patients with lung cancer than in patients with BPNs (Benign pulmonary nodules), and the difference was not significant (cancer vs benign: 2053.46 vs 1611.06 pg/ml, P=0.209)." (PMID 35769715, 2022). "Patients with early-stage lung cancer had lower plasma CXCL14 levels than patients with lung cancer at later stages (stage I: 1452.40 pg/ml, stage II: 1898.00 pg/ml, stage III: 2231.00 pg/ml, stage IV: 2661.62 pg/ml, P=0.041)." (PMID 35769715, 2022). "In our study, we used plasma samples to further confirm CXCL14 expression in a cohort of lung cancer patients." (PMID 35769715, 2022). "Re-expression or overexpression of CXCL14 in lung cancer cells can suppress tumor growth in vivo in an autocrine or paracrine manner." (PMID 35769715, 2022). "ROC curve analysis showed that plasma CXCL14 achieved an AUC of 0.9464 (95% confidence interval [CI], 0.9209–0.9719) at a cutoff point of 746.0 pg/ml for diagnosis of lung cancer, with 87.4% sensitivity and 85.0% specificity." (PMID 35769715, 2022). "And the level of CXCL14 in urine can be used as a marker for early diagnosis of lung cancer at a cutoff point of 564.8 pg/ml." (PMID 35769715, 2022). "Compared with healthy volunteers, urine CXCL14 levels were 1.7 times higher in lung cancer patients." (PMID 35769715, 2022). "Further, Plasma level of CXCL14 were also significantly increased in patients with stage I lung cancer (P<0.0001)." (PMID 35769715, 2022). "ROC curve analysis showed that urine CXCL14 achieved an AUC of 0.647 (95% confidence interval [CI], 0.5829–0.7111) at a cutoff point of 888.7 pg/ml for diagnosis of stage I lung cancer, with 39.24% sensitivity and 90.16% specificity." (PMID 35769715, 2022). "Correlation between CXCL14 expression in tissue and clinicopathological characteristics of lung cancer patients." (PMID 35769715, 2022). "We assessed correlations between the CXCL14 level in plasma and the clinicopathological features of lung cancer patients." (PMID 35769715, 2022). "ROC curve analysis showed that plasma CXCL14 achieved an AUC of 0.9353 [95% confidence interval (CI), 0.9034–0.9672] at a cutoff point of 840.3 pg/ml for diagnosis of stage I lung cancer, with 81.02% sensitivity and 92.5% specificity." (PMID 35769715, 2022). "ROC curve analysis showed that urine CXCL14 achieved an AUC of 0.6476 (95% confidence interval [CI], 0.5934–0.7091) at a cutoff point of 564.8 pg/ml for diagnosis of lung cancer, with 50.0% sensitivity and 78.69% specificity." (PMID 35769715, 2022). "The plasma CXCL14 concentration was slightly higher in patients with lung cancer than in patients with BPNs (Benign pulmonary nodules), but the difference was not significant (cancer vs benign: 2053.46 vs 1611.06 pg/ml, median, P=0.209)." (PMID 35769715, 2022). "Compared with healthy volunteers, plasma CXCL14 levels were 65.7 times higher in lung cancer patients." (PMID 35769715, 2022). "Consistent with the results in plasma, CXCL14 levels were also higher in the urine of lung cancer patients than in the control group." (PMID 35769715, 2022). "The median CXCL14 concentration in the plasma of lung cancer patients was 2053.46 pg/ml and that in healthy volunteers was 31.25 pg/ml." (PMID 35769715, 2022). "Overall, the level of CXCL14 in plasma can be used as a marker for early diagnosis of lung cancer at a cutoff point of 746.0 pg/ml." (PMID 35769715, 2022). "ROC curve analysis showed that urinary CXCL14 predicted the diagnosis of lung cancer with an AUC of 0.6476 (95% confidence interval [CI], 0.5934–0.7091) at a cutoff point of 564.8 pg/ml." (PMID 35769715, 2022). "Plasma CXCL14 predicts the diagnosis of lung cancer with an AUC of 0.9464 at a cutoff point of 746.0 pg/ml." (PMID 35769715, 2022). "In oral cancers, lung cancers, and head and neck cancers, C-X-C Motif chemokine ligand 14 (CXCL14) functions as a tumor suppressor; it also induces growth of prostate and breast cancers." (PMID 34376762, 2021).
lung carcinoma (continued). "RhoBTB2, an atypical member of the Rho family, as a tumour suppressor which is downregulated in a large proportion of breast and lung cancers, is able to positively regulate CXCL14 expression in normal and cancerous epithelial cells." (PMID 26733763, 2016). "Analysing a prospective cohort of blood samples from lung cancer patients across different stages, we uncovered that CXCL14 in plasma predicted the occurrence of metastasis and demonstrated similar diagnostic efficacy to typical tumour markers (e.g., CEA, Cyfra21‐1, SCC, etc.)." (PMID 40162549, 2025). "Similarly, CXCL14 enhances the propensity of cancer cells toward bone and/or recruits bone marrow cells around metastatic cancer cells to promote bone metastasis in lung cancer." (PMID 38714539, 2024). "Therefore, understanding the mechanisms responsible for CXCL14-promoted metastasis in lung cancer and identifying the key factors involved will identify new therapeutic targets." (PMID 37056937, 2023). "CXCL14 is overexpressed in lung cancer in the TCGA database and the GEO dataset." (PMID 37056937, 2023). "Furthermore, the migration of CXCL14-promoted lung cancer cells was determined in vitro and in vivo." (PMID 37056937, 2023). "Moreover, transfection of ACKR2 siRNA prevented CXCL14-activated PLCβ3, PKCα, and c-Src phosphorylation, indicating that CXCL14 promoted lung cancer cell migration and EMT through activation of ACKR2/PLCβ3/PKCα/c-Src signaling pathway." (PMID 37056937, 2023). "Furthermore, the inhibition of PLCβ3, PKCα, and c-Src phosphorylation reversed CXCL14-induced transcriptional activity of NF-κB in lung cancer cells." (PMID 37056937, 2023). "However, few studies have explored the function of CXCL14 and its specific receptor in lung cancer metastasis." (PMID 37056937, 2023). "Interestingly, the IHC scores of lung cancer tissue array were similar to Meta-analysis and GEO datasets indicated that CXCL14 expression was significantly upregulated in the lung cancer tissues." (PMID 37056937, 2023). "High expression of CXCL14 in stroma may be a prognostic factor for lung cancer in predicting poor overall survival and disease-free survival." (PMID 35769715, 2022). "Meanwhile, in lung cancer cells, CXCL14 is usually perceived to be downregulated." (PMID 35769715, 2022). "We discovered significantly elevated CXCL14 levels in the plasma of patients with lung cancer." (PMID 35769715, 2022). "Our study suggests that the plasma CXCL14 level may be a potential marker to assist lung cancer diagnosis with relatively satisfying sensitivity and specificity." (PMID 35769715, 2022). "Highly expressed CXCL13 and CXCL14 in lung cancer tissues were also reported in other studies." (PMID 35844446, 2022). "The urine CXCL14 level in lung cancer patients was increased (P<0.0001)." (PMID 35769715, 2022). "The urinary CXCL14 level in lung cancer patients was higher than that in healthy volunteers." (PMID 35769715, 2022). "The plasma CXCL14 level in lung cancer patients was significantly increased (P<0.0001)." (PMID 35769715, 2022). "Further, urine level of CXCL14 were also increased in patients with stage I lung cancer (P<0.0001)." (PMID 35769715, 2022). "Furthermore, CXCL14 expression is inhibited by DNA methylation in lung cancer cells, resulting in reduced tumor growth." (PMID 35330734, 2022). "TAMs potentiate bone metastasis, which has been shown for example in lung cancer, where macrophages migrate towards CXCL14 expressing bone-seeking cells more efficiently than towards parental lung cancer cells, and deletion of macrophages suppresses bone metastasis of lung cancer." (PMID 34204474, 2021). "In addition to OPG, other tumour-secreted proteins, such as osteopontin and CXCL14, have critical roles in the regulation of bone metastasis in lung cancer, either through exosomal trafficking or directly through paracrine signalling." (PMID 34215717, 2021).
lung carcinoma (continued). "Additionally, the enrichment of the TGF-β signaling pathway in AS_STAS may suggest that CXCL14-induced fibroblast production of TGF-β enhances lung cancer invasion and migration." (PMID 40786043, 2025). "However, the function of CXCL14 in lung cancer progression is still unclear." (PMID 37056937, 2023). "Importantly, CXCL14 overexpressed profoundly enhanced lung cancer cell metastasis." (PMID 37056937, 2023). "However, CXCL14 has been shown to be involved in osteolytic bone metastasis from lung cancer." (PMID 36012586, 2022). "The results illustrated that NF-κB activation is necessary for CXCL14-promoted migration and EMT in lung cancer cells." (PMID 37056937, 2023). "The results revealed that chemokine CXCL14 promotes EMT and migration through ACKR2 in lung cancer for the first time." (PMID 37056937, 2023). "Compared with healthy controls, the levels of CXCL14, CXCL13 and CCL20 were increased in the plasma of patients with lung cancer." (PMID 35769715, 2022). "Again, many of the immune-modulatory genes differentially expressed in the mouse model were site-specifically recapitulated, e.g., higher CCL2, CXCL5, CXCL9, CXCL11, CXCL14, CXCL17, and IDO1 in lung cancers and higher CXCL12, FGL1, and LAG3 in liver cancers." (PMID 33985562, 2021). "Additionally, CXCL14 facilitates EMT and subsequent cell migration in lung cancer by transactivating the ACKR2/PLC/PKC/c‐Src signalling pathway." (PMID 40162549, 2025). "Additionally, CXCL14 promoted the transcriptional activity of NF-κB, which is related to tumor migration and EMT of lung cancer cells." (PMID 37056937, 2023). "Next, lung cancer cells transfected with the ACKR2 siRNA or incubated with ACKR2 neutralized antibody markedly abolished CXCL14‐induced cell migration and cell movement, but not CXCR4, and GPR85." (PMID 37056937, 2023). "Using single-cell mRNAseq data, CXCL14-expressing fibroblasts have previously been detected in HNSCC, melanoma, and lung cancer lesions and are presumed to have immunosuppressive effects; the latter explained the association of their presence with poorer prognosis." (PMID 37076857, 2023). "CXC chemokine ligand 14 (CXCL14) expression in tumors and nontumor regions of lung tissues from 133 lung cancer cases was detected by immunohistochemical (IHC) staining and immunofluorescence (IF) staining of formalin fixed paraffin-embedded (FFPE) tissues." (PMID 35769715, 2022). "The results of the present study showed that MDK, WFDC2, and CXCL14 were upregulated in early-stage LUAD and upregulated expressions of three secreted proteins promoted the proliferation of lung cancer cells, suggesting that these proteins might be involved in the tumorigenesis of LUAD." (PMID 36721112, 2023). "However, no studies have been conducted to demonstrate the level of CXCL14 and its clinical role in a large cohort of urine samples from patients with lung cancer." (PMID 35769715, 2022). "Additionally, ACKR2 was involved in CXCL14-triggered phospholipase Cβ3 (PLCβ3), protein kinase Cα (PKCα), and proto-oncogene c-Src signaling pathway and subsequently upregulated nuclear factor κB (NF-κB) transcription activity leading to EMT and migration of lung cancer cells." (PMID 37056937, 2023). "In human lung cancer cell line NCI-H460, which does not express potential target GPCRs for CXCL14, CXCL14 stimulates NF-κB activity to promote its proliferation and migration by binding to some glycoproteins on cell surface." (PMID 26733763, 2016).